OR10V1 (olfactory receptor family 10 subfamily V member 1)
Description:
Odorant receptor.
Synonyms: OR11-256
Tractability: Antibody: UniProt places it where antibodies can reach, with medium confidence; UniProt predicts a signal peptide or a membrane-spanning region; its Gene Ontology location is reachable by antibodies, with medium confidence.
Gene: Protein-coding gene on chromosome 11 (59,712,916 to 59,713,845, reverse strand). Ensembl gene ENSG00000172289.
Subcellular location: Cell membrane
Pathways (Reactome):
Sensory Perception: Expression and translocation of olfactory receptors
Gene Ontology:
Molecular function: odorant binding; olfactory receptor activity; G protein-coupled receptor activity
Biological process: sensory perception of smell; detection of chemical stimulus involved in sensory perception of smell; G protein-coupled receptor signaling pathway
Cellular component: plasma membrane; membrane
Genetic constraint (gnomAD): Loss-of-function variants: 1 observed, 1.44 expected, observed/expected ratio (o/e) 0.7, 90% interval 0.21 to 1.84. That is too few expected variants to judge how well the gene tolerates losing a copy. Missense variants: 389 observed, 396.37 expected, observed/expected ratio (o/e) 0.98, 90% interval 0.9 to 1.07. Synonymous variants: 139 observed, 156.88 expected, observed/expected ratio (o/e) 0.89, 90% interval 0.77 to 1.02.
Homologues: Orthologues: chimpanzee OR10V1 (99% identical), mouse Or10v1 (90% identical), rat Or10v1 (88% identical), rabbit OR10V1 (87% identical), pig OR10V1 (86% identical), dog OR10V1 (85% identical). Paralogues in human: OR10Q1 (54% identical), OR10W1 (46% identical), OR9G4 (46% identical), OR5A1 (44% identical), OR8I2 (44% identical), OR5M10 (43% identical), OR5AR1 (43% identical), OR5AU1 (43% identical), OR5M1 (43% identical), OR8H1 (43% identical), OR5AN1 (42% identical), OR5AP2 (42% identical), and 84 more.